CCND1 (cyclin D1)
Diseases named in the same sentence as CCND1 in open-access papers (continued):
Sharing a sentence is not in itself a finding about the gene and the disease.
adenocarcinoma (38 papers, 2004 to 2025). A common cancer characterized by the presence of malignant glandular cells. "CCND1 rs9344 was significantly associated with adenocarcinoma (ADC) patients in the recessive model." (PMID 38589850, 2024). "Increased risk for SCC or adenocarcinoma has been reported in HS patients with abnormal CCND1 expression, possibly due to chronic inflammation." (PMID 38792557, 2024). "This pilot study was carried out in an unusual sub-type of CC i.e., adenocarcinoma to understand the role of altered Cyclin D1 induced by activated HPV-16 associated Notch signaling pathway in cell cycle regulation." (PMID 30903019, 2019). "In our clinical samples, cyclin D1 overexpression was significantly associated with RFS in stage II-IIIA adenocarcinoma." (PMID 26681199, 2015). "Several phase 1 and 2 studies have implicated cyclin D1 in esophageal malignancy, and overexpression of cyclin D1 protein has been reported in up to 64% of adenocarcinomas and associated Barrett epithelia 110,111." (PMID 17576439, 2006). "In keeping with this notion, E47 inhibited expression of Cyclin E1 and Cyclin D1 and upregulated expression of cell-cycle inhibitor p21 in adenocarcinoma A549 and H1299 cells." (PMID 33833226, 2021). "Overexpression of cyclin D1 and decrease of p16 have been reported to be frequently observed in both adenocarcinoma and adenomatous hyperplasia." (PMID 32945604, 2020). "We recommend vorinostat as an adjuvant chemotherapeutic agent for patients with stage II-IIIA adenocarcinoma in which cyclin D1 is overexpressed." (PMID 26681199, 2015). "Overexpression of cell cycle regulatory protein, cyclin D1, was detected in patients with adenomatous polyps and adenocarcinomas demonstrating its importance in colon carcinogenesis." (PMID 23118901, 2012). "In SCC positive cyclin D1 expression was detected in 21 from 24 cases (87.5%) and in adenocarcinoma in 12 from 15 (80%)." (PMID 22024187, 2011). "In accordance, Mcm2, Fen1, Ube2c and cyclin D1 proteins were also relatively higher in the MDA-F471 mouse adenocarcinoma cells compared to the normal Gprc5a−/− cells as revealed by the western blotting analysis." (PMID 20686609, 2010). "The present study suggests that cyclin D1 may be an independent prognostic factor for recurrence-free survival in stage II-IIIA adenocarcinoma of lung and its expression may be modulated by vorinostat." (PMID 26681199, 2015). "The adenocarcinomas that developed both on and off tamoxifen in this study demonstrated similar patterns of gene expression with both detectable hormone receptor expression, principally ERα, and cyclin D1 expression." (PMID 24575359, 2012). "We utilized MMTV-rtTA/tetO-HER2 transgenic mice, which develop spontaneously arising, cyclin D1 and Rb-expressing, CDK4/6i–sensitive adenocarcinomas within developmentally normal, mature mammary glands." (PMID 38047585, 2024). "We initially focused on patient 29, who had a pT3N0 diffuse subtype adenocarcinoma arising from the gastroesophageal junction with amplification of MET, FGFR2, and CCND1 (eFigure 4A in the Supplement)." (PMID 32338752, 2020). "Several of the identified mGISTIC regions harbored known or putative adenocarcinoma driver candidates, such as EGFR, MDM2, KRAS, MYC, TERT, MET, CCND1, NKX2-1/TITF1, CDK4, ERBB2, ID1, RB1, CDKN2A and PTEN." (PMID 24205279, 2013). "We didn't reveal differences in cyclin D1 and galectin-3 expression in SCC and adenocarcinoma patients." (PMID 22024187, 2011).
adenocarcinoma (continued). "We analyzed the prognostic value of cyclin D1 expression in all patients with NSCLC and separately in patients with SCC and adenocarcinoma, and separately in every stage, but we didn't find any statistical significant differences." (PMID 22024187, 2011). "The median duration of RFS was 15 months and 25 months for adenocarcinoma patients with and without cyclin D1 overexpression, respectively." (PMID 26681199, 2015). "Moreover we analyzed the prognostic value of cyclin D1 expression and galectin-3 in all examinated patients and separately in SCC and in adenocarcinoma and in all stages, but we didn't find any statistical differences." (PMID 22024187, 2011).
breast (9 papers, 2016 to 2025). "Aside from cyclin D1’s well-established role in cell cycle transition and cell growth, a recent study revealed that overexpression of cyclin D1 enhanced the formation of CSCs in liver cancer." (PMID 30918246, 2019).
benign tumors (7 papers, 2011 to 2024). "Presently, alterations in MEN1 and CCND1 are still the main genetic alterations associated with the development of sporadic benign tumors (accounting for approximately 30% of the cases)." (PMID 22567348, 2011). "Similarly, cyclin-D1 and p35 gene products, Ccnd1 and Cdk5r1, were up-regulated in benign tumors." (PMID 25900242, 2015).
cardiovascular disease (7 papers, 2017 to 2025). "Together, these results suggest that epimutations at important cell cycle genes such as CCND1 could provide a molecular link for how both cardiovascular disease and limb malformation may be present in patients." (PMID 34246298, 2021).
hematological malignancies (7 papers, 2018 to 2025). "For this, we first dissected the epigenomic landscape of two loci that are commonly translocated in hematological malignancies: CCND1 at 11q13 and the IGH locus at 14q32." (PMID 34933939, 2022). "Interestingly, all 5 RNA samples harvested from patients in CR of their hematological malignancies and CCND1 positive at diagnosis were categorized at low level of SOX11 expression." (PMID 29484276, 2018). "In light of the key roles played by CYCLIN D1 and CK2 in hematological malignancies, it is not surprising that clinical trials aimed at testing small molecule inhibitors of these and other proteins in combination has gained increasing momentum." (PMID 30701029, 2018).
hematologic neoplasm (6 papers, 2017 to 2024). "Its extract MTE also exerts a potent potential of inducing apoptosis through upregulating proapoptotic Bax, caspase‐9, and caspase‐3 and downregulating cyclin D1 and antiapoptotic Bcl‐2 in hematologic neoplasm cells." (PMID 36756719, 2023). "Subsequently, the 5th edition of the WHO classification of hematological neoplasms (WHO-HAEM5) has adopted this separator for translocations which involve conventional genes and IG and TR loci in hematological neoplasms, also italicizing these genes and IG and TR loci (e.g IGH::MYC and IGH::CCND1)." (PMID 38664547, 2024).
neurodegenerative disease (5 papers, 2018 to 2023). A disorder of the central nervous system characterized by gradual and progressive loss of neural tissue and neurologic function. "Our results suggest that astrocytes may control neuronal functions and proliferation by modulating, in normal or altered conditions such as aging or degenerative diseases, cyclin-D1 expression." (PMID 29740309, 2018). "We suggest that astrocytes may modulate neuronal functions, in normal and/or in altered conditions such as aging or degenerative diseases, by mechanisms implying cyclin-D1 expression." (PMID 29740309, 2018).
colon (4 papers, 2019 to 2022). "Meanwhile, in the progression of gastrointestinal tumor, the synergy between NR5A21 and β-catenin/TCF4 signaling upregulate the expression of cyclin D1, cyclin E1, and c-Myc which is the downstream targets of the canonical Wnt signaling." (PMID 35633416, 2022). "In addition, Gröschel and colleagues found that 1,25(OH)2D3 reduces nuclear β-catenin levels in LT97 colon microadenoma cells and thus downregulates the expression of Wnt target genes such as BCL2, CCND1/cyclin D1, SNAI1, CD44, and LGR5." (PMID 33227961, 2020).
cardiac disease (2 papers, 2021 to 2023). "CCND1 is a proto-oncogene that manages progression via the G1-S phase of the cell cycle, and its involvement in heart diseases has been reported." (PMID 37372424, 2023). "CCND1’s involvement in cardiac disease is supported by its presence in both the cell cycle and Wnt signaling and previous observations of upregulation in DCM." (PMID 34246298, 2021). "Among these four genes, CCND1 was the only one not linked to IDCM or related heart disease in DisGeNET; therefore, according to our investigation, CCND1 may be introduced as a potential biomarker for IDCM." (PMID 37372424, 2023).
colon polyps (2 papers, 2016 to 2023). "Western blot analysis of adenomatous polyps in myricetin-treated mice showed an inhibition of cyclin D1 in both the small intestinal and colonic polyps by 76.6% (p < 0.01), and 88.4% (p < 0.01), respectively." (PMID 27507058, 2016). "Interestingly, in colon polyps, cyclin D1 is overexpressed in comparison to normal tissue and may be linked with cell cycle-promoting activity." (PMID 37316878, 2023).
head and neck tumors (2 papers, 2022 to 2025). "In contrast, the expression of CCND1 in head and neck tumors showed no significant variation, but its elevated expression correlated with the 5-year survival rate, while it did not influence disease-free survival." (PMID 40302810, 2025).
hematologic cancers (2 papers, 2015 to 2025). "These preclinical results demonstrate the therapeutic potential of targeting POLΘ in oncogene-driven hematologic cancers, especially in MCL, where cyclin D1 overexpression is ubiquitous and ATM deficiency is common, but may extend to other oncogene-driven hematologic cancers." (PMID 40608419, 2025). "As expected, cyclin D1 was constitutively expressed in the ten MCL cell lines, while not detectable in other hematological cancer cell lines." (PMID 25428911, 2015).
inflammation (1 paper, 2016). Aberrant reaction of the microcirculation characterized by movement of fluid and leukocytes from the blood into extravascular tissues. "Curcumin Nano emulsions show 85% inhibition of 12-O-Tetradecanoylphorbol-13-acetate (TPA)-induced mouse ear inflammation as well as the inhibition of cyclin D1 expression." (PMID 27608040, 2016).
CCND1 also shares sentences with these, for which no sentence is quoted: Insulin resistance (5 papers); papillary carcinoma (5); clear cell carcinoma (4); cutaneous squamous cell carcinoma (4); intrahepatic cholangiocarcinoma (4); adenocarcinoma of the uterine cervix (3); Fanconi anemia (3); gastritis (3); gastro‐intestinal stromal tumours (3); hepatitis B (3); idiopathic pulmonary fibrosis (3); metabolic disorders (3); ovarian endometrioid adenocarcinoma (3); penile cancer (3); prolymphocytic leukemia (3); superficial spreading melanoma (3); Uterine leiomyoma (3); alcohol abuse (2); anaplastic oligodendroglioma (2); Ataxia (2); autosomal dominant polycystic kidney disease (2); calcification (2); chronic kidney disease (2); coronary artery disease (2); Crohn disease (2); emphysema (2); endometrial polyp (2); Esophageal Diseases (2); follicular carcinoma (2); giant cell tumor (2).
A further 173 diseases each share a sentence with CCND1 in 2 papers or fewer.